ALB (albumin)
Diseases named in the same sentence as ALB in open-access papers (continued):
Sharing a sentence is not in itself a finding about the gene and the disease.
neurological diseases (36 papers, 2015 to 2026). "ALB is thought to be associated with many neurological disorders because of its ability to modulate the hemodynamic properties of the cerebral circulation and its direct neuroprotective functions in the neuronal and glial cells." (PMID 37153679, 2023). "Since a relevant proportion of neurological diseases are associated with an elevation of the albumin quotient, evaluation of the intrathecal fraction of FLCκ based on the hyperbolic reference range should be the method of choice for disease-independent evaluation." (PMID 36421703, 2022). "The IA-group served as the first control for any changes of albumin redox state that might occur due to the extracorporeal circuit and the non-treatment group as a second control for a maybe already altered albumin redox state due to the underlying neurological disease." (PMID 35842435, 2022). "Therefore, our findings on ECM remodeling upon albumin extravasation may provide a clue on pathogenic mechanisms for a broad spectrum of neurological disorders that involve BBB dysfunction." (PMID 28794441, 2017). "In recent years, an increasing amount of evidence has indicated that albumin plays a crucial role in neurological diseases." (PMID 40391213, 2025). "It is noteworthy that indicators reflecting liver function, such as DBIL, NBIL, TP, and ALB, along with markers associated with liver glucose and lipid metabolism, such as GLU and APOA1, play significant roles in predicting nervous system diseases." (PMID 40739302, 2025). "Considering that MS is a neurological disorder, exploring the albumin levels in CSF would indeed provide a novel insight." (PMID 38915402, 2024). "In contrast, none of the control mice that were challenged with bovine serum albumin via the same routes developed any neurological disease or neuropathology." (PMID 31230104, 2019). "This novel technique, combining albumin-based NBs and LoFreqUS offers a promising, efficient, targeted, and non-invasive solution for central nervous system gene therapy, potentially transforming the treatment landscape for neurological disorders." (PMID 38334557, 2024). "However, there was a significant statistical difference among patients with different albumin levels with respect to biliary etiology and concomitant neurologic disease though it occurred in a few patients." (PMID 29147647, 2017). "Accordingly, these findings present the valuable capabilities of albumin and suggest that CNS-targeted drug delivery might be possible through nasal route application by utilizing serum albumin as a carrier system to deliver the drug for the treatment of neurological diseases." (PMID 39458651, 2024). "Moreover, little is known about the albumin redox state of patients with neurological disorders." (PMID 35842435, 2022). "Albumin is a powerful antioxidant with free radical scavenging activity, has a neuroprotective role in neurological diseases, and its level is reduced in MS patients; therefore, its increase may have contributed to the reduction in OS in the group who received integration." (PMID 34287336, 2021). "Compared with similar metrics, like UAR (the uric acid to albumin ratio) and NLR (the neutrophil-to-lymphocyte ratio), SUA/SCr has a more striking predictive value in predicting neurological disorders, especially in patients with acute ischemic stroke." (PMID 40671786, 2025). "In recent years, biomarkers such as albumin, gamma-glutamyl transferase (GGT), total bilirubin (TBIL), uric acid (UA), and the urea nitrogen-to-creatinine ratio have emerged as significant indicators of oxidative stress in the context of neurological diseases." (PMID 40391213, 2025). "We selected a control cohort of 68 subjects matched by age, BMI and sex from the individuals without a neurological disease and with a CSF/serum albumin ratio of <(4 + age/15) × 10−3 (as recommended)." (PMID 39595074, 2024).
neurological diseases (continued). "The CSF/serum quotient of albumin was found to increase during systemic inflammation, but only in the presence of CSF abnormality; it is possible that leakage was not seen in the absence of neurological disease because albumin is too large a molecule." (PMID 34594000, 2021). "In the present study, three food antigens previously related or not related to neurologic disorders (egg albumin, casein, and Neu5Gc) were selected for the determination of antibodies against them in the cerebrospinal fluid (CSF) and serum of patients with AD and healthy individuals." (PMID 40867530, 2025).
inflammation (34 papers, 2010 to 2026). Aberrant reaction of the microcirculation characterized by movement of fluid and leukocytes from the blood into extravascular tissues. "In the Pdpn-het KO mice, aspirin-induced jejunal inflammation produced a significant leakage of the intravenous administration of FITC-albumin into the jejunal lumen." (PMID 40737946, 2025). "Chronic inflammation has also been shown to impair albumin synthesis, thereby further compromising patient health." (PMID 41048521, 2025). "TMAO also decreased with the increase of fecal calprotectin, a marker of intestinal inflammation; and low albumin levels, which speaks in favor of the relationship between TMAO and the severity of the pathological process." (PMID 39407853, 2024). "Likewise, the inverse association between ALB and MASLD highlights how chronic liver inflammation impairs albumin synthesis and function, contributing to disease severity." (PMID 40655480, 2025). "Thus, in the Pdpn-het KO mice, aspirin-induced jejunal inflammation resulted in a significant leakage of the FITC-albumin into the jejunal lumen." (PMID 40737946, 2025). "A consistent lack of acute local pulmonary inflammation was observed in terms of the broncho-alveolar lavage fluid parameters examined (i.e. LDH, albumin, and macrophage activation) in animals exposed to WC-Co NP; however, significant acute pulmonary inflammation was observed in the CeO2 NP group." (PMID 25738830, 2015). "Chronic inflammation, marked by elevated cytokines like IL-6 and CRP, further suppresses albumin production and accelerates its breakdown." (PMID 40703630, 2025). "FITC-labelled formaldehyde-treated serum albumin (FITC-FSA), a model ligand for LSEC scavenger receptors was administered intravenously into Glmpgt/gt mice, aged 4 months (peak of liver inflammation), 9–10 month, and age-matched Glmpwt/wt mice." (PMID 37910485, 2023). "As PLE is considered a more severe form of intestinal inflammation, the positive correlation between HIS, PHE and TRP and albumin serum concentration can be considered as an indicator of the severity of loss from the gastrointestinal tract." (PMID 32321505, 2020). "Considering the magnitude of the differences in BAL neutrophils and albumin levels, our results suggest that TSG-6 has a mild, protective role during acute lung inflammation." (PMID 29855321, 2018). "Using this method, we demonstrated that ectopic expression of C/A MYPT1 reduces lung inflammation (MPO staining) and attenuates LPS-induced vascular permeability (Evans Blue Dye albumin (EBA) extravasation into the lung)." (PMID 27976727, 2016). "In CHB patients, the correlation analysis was also made between serum sST2 levels and several probable serum markers indicating severity of liver inflammation: ALT, HBV DNA, hs-CRP, serum total bilirubin, albumin levels, PLT, prothrombin time, and age." (PMID 26632683, 2015). "Pulmonary inflammation and damage, measured as the number of polymorphnuclear leukocytes (PMNs) or lactate dehydrogenase activity (LDH) and albumin in BAL, increased rapidly (1 day post) after inhalation of MWCNTs and declined slowly with time post-exposure." (PMID 23895460, 2013). "Studies to evaluate effects of cytomix treatment demonstrated that mice developed significant acute lung inflammation (peaking at 48 h) along with transient edema (based on albumin increases in BAL fluid without LDH increase)." (PMID 23151036, 2012). "In the present study, WC-Co NPs did not induce significant acute pulmonary inflammation, compared to the vehicle control, in the assessment of LDH activity and albumin content in the BAL fluid following 24-hr exposure at doses of 50–500 μg per rat." (PMID 25738830, 2015).
hematological malignancies (32 papers, 2014 to 2026). "Retrospective studies of hematologic malignancies patients undergoing HDMTX therapy indicate low ALB levels are significantly associated with delayed MTX clearance." (PMID 40832604, 2025). "We initially explored the associations of serum albumin levels withsusceptibility to the development of pulmonary mucormycosis and its outcome incontemporaneous high-risk hematological malignancy patients at a major tertiary carecancer center in the US." (PMID 39678331, 2024). "In addition, four factors, including increased heart rate, high blood urea nitrogen level, low serum albumin level, and hematologic malignancy were independently associated with 60-day death or colectomy in multivariable analyses." (PMID 41463754, 2025). "The PNI calculated from the serum albumin level and peripheral blood lymphocyte count is now widely considered to be associated with the prognosis of patients with some solid malignant tumors and hematological malignancies." (PMID 36276809, 2022). "Multivariable analysis identified four factors independently associated with 60-day death or colectomy: heart rate, blood urea nitrogen level, albumin level, and hematologic malignancy." (PMID 41463754, 2025). "Our findings show that the D-dimer/albumin ratio is a strong predictor of PE in hematologic malignancies." (PMID 41156207, 2025). "The other related risks were an increased SOFA score, decreased serum albumin, and presence of solid and hematologic malignancies and septic shock." (PMID 34966562, 2021). "Most of the previous studies were limited to specific populations, such as patients with low serum albumin or hematological malignancies." (PMID 34959640, 2021). "This is the first study to establish the influence of plasma albumin level and co-administration of omeprazole and voriconazole on dose-adjusted concentration of voriconazole in patients with hematologic diseases." (PMID 32899425, 2020). "Despite a high negative predictive value, different patient characteristics (i.e. hematological diseases) and interventions (i.e. albumin or immunoglobulin administration, hemodialysis) are responsible for its reported low specificity." (PMID 24559080, 2014). "Inflammatory-nutritional markers including the modified Glasgow Prognostic Score (mGPS), the CRP × fibrinogen/albumin ratio (CFA) and the C-reactive protein-albumin ratio (CAR) are closely associated with prognosis in patients with various solid tumors and some hematological malignancies." (PMID 41586228, 2025). "However, the comparison within groups demonstrated that in patients with hematological malignancies prealbumin and albumin concentrations were significantly higher after treatment that before." (PMID 39619813, 2024). "Serum albumin has been included in the modified Glasgow score of hematological malignancies." (PMID 30083224, 2018). "In concurrence with results from previous studies on hematological malignancies, univariate analysis revealed CRP and albumin as individual components of the GPS and CAR to have significant impact on OS (p < 0.0001; p < 0.0001)." (PMID 34415426, 2022). "Therefore, the primary objective of our study was to investigate the impact of low serum albumin level (SAL) on outcomes, including mortality, AKI, and duration of ICU stay, in critically ill children with oncologic/hematologic diseases." (PMID 40567610, 2025). "Therefore, the objective of this study was to investigate the impact of low serum albumin levels (SAL) on outcomes, including mortality and AKI, in critically ill children with oncologic/hematologic diseases." (PMID 40567610, 2025). "The C-reactive protein-albumin-lymphocyte (CALLY) index, integrating markers of inflammation, nutritional status, and immune competence, has demonstrated prognostic relevance in solid tumors; however, its relevance in hematologic malignancies remains unexplored." (PMID 41827779, 2026).
peripheral neuropathy (28 papers, 2013 to 2026). A disorder affecting the peripheral nervous system. "There also appears to be a trend between elevated serum albumin concentrations and high peripheral neuropathy risk, potentially due to maleimide exchange enabling albumin-MMAE conjugate formation." (PMID 37727735, 2023). "Of note, albumin-bound paclitaxel and cisplatin also have toxic and side effects, including bone marrow suppression, extremities numbness caused by peripheral neuropathy, renal toxicity and gastrointestinal reactions." (PMID 35979370, 2022). "Studies among HIV infected cohorts have reported a significant association of low serum albumin levels with presence of peripheral neuropathy symptoms in HIV-infected individuals." (PMID 27855635, 2016). "This study presented a case of peripheral neuropathy induced by albumin-bound paclitaxel in conjunction with cisplatin and tislelizumab in an NSCLC patient." (PMID 39296984, 2024). "According to the National Cancer Institute-Common Toxicity Criteria (NCI-CTC) and the World Health Organization (WHO) grading criteria, the peripheral neuropathy induced by albumin-bound paclitaxel is categorized as grade 3." (PMID 39296984, 2024). "In conclusion, this study reported a case of peripheral neuropathy induced by albumin-bound paclitaxel in the treatment of NSCLC." (PMID 39296984, 2024). "Nanoparticle albumin-bound paclitaxel (nab-PTX), a novel taxane formulation, was developed to avoid cremophor/ethanol-associated toxicities including peripheral neuropathy and hypersensitivity." (PMID 33811599, 2021). "Validity of albumin, eGFR, and creatinine in diagnosis of peripheral neuropathy." (PMID 33313023, 2020). "This may be due to the fact that the model was based on several key predictive factors-e.r., urine albumin, peripheral neuropathy, abnormal blood glucose, and BMI — that have high generalizability and clinical interpretability across ethnicities, geographical locations, and healthcare system." (PMID 41473241, 2025). "In 1 of these excluded cases, the observed adverse events included lower extremity peripheral neuropathy, high cholesterol, cracked skin on the hands, reduced magnesium, chills, fever, elevated CRP level, slightly elevated white blood cell count, and reduced pre-albumin level." (PMID 35949598, 2022).
neurodegenerative disease (25 papers, 2011 to 2025). A disorder of the central nervous system characterized by gradual and progressive loss of neural tissue and neurologic function. "Several lines of evidence point toward a key role of HOCl-modified serum albumin in the progression of chronic inflammation, a hallmark of various degenerative diseases." (PMID 31298656, 2019). "If this is the case, it will provide a great opportunity to employ albumin for nose-to-brain route delivery, allowing for the treatment of various neurodegenerative diseases." (PMID 39458651, 2024). "Neurodegenerative diseases were treated with a new compound, the interaction of viologen dendrimers with HSA (human serum albumin) has been examined, and it also had the inhibition of acetylcholinesterase and butyrylcholinesterase." (PMID 38174062, 2023). "Recently, the role of albumin has been revisited, with an accent of its oxidized and glycated derivatives in the development of cardiovascular and neurodegenerative diseases." (PMID 36361826, 2022). "The liver growth factor (LGF) is a hepatic mitogen and albumin–bilirubin complex that exhibits remarkable protective effects in preclinical models of hepatic and extrahepatic diseases, and neurodegenerative diseases." (PMID 35745683, 2022). "Liver growth factor is an albumin–bilirubin complex that exhibits remarkable neuroprotective, anti-inflammatory, and anti-oxidant activities in several models of neurodegenerative diseases." (PMID 33276671, 2020). "The aggregate changes in CSD-S microglia were similar to those resulting from LPS administration, neurodegenerative disease states, albumin infusion, and other CNS-centric inflammatory challenges." (PMID 30050134, 2018). "Collectively, these results provide evidence for a new mechanism by which microglial cells promote death of neuronal cells through synthesis and secretion of AGE-albumin, thereby likely contributing to neurodegenerative diseases such as AD." (PMID 22662249, 2012). "Moreover, albumin has tied up with many neurodegenerative diseases because of its direct protective action on neuron." (PMID 37034095, 2023). "In addition to the ability of chelating free Zn2+, albumin also demonstrates anti-inflammation properties, like in degenerative diseases." (PMID 36384553, 2022). "The overestimated proportion of albumin dimeric and oligomeric forms may be the first symptom of the development of neoplastic or neurodegenerative diseases." (PMID 35897662, 2022). "Meanwhile, albumin demonstrated anti-inflammation properties, like in degenerative diseases." (PMID 36384553, 2022). "Additionally, albumin has antioxidant and anti-inflammatory effects, which may counteract the significant oxidative stress and neuroinflammation accompanying neurodegenerative diseases." (PMID 41346383, 2025). "Based on Bonferroni correction, antioxidant biomarkers in our study did not significantly contribute to neurodegenerative diseases, but there were some notional correlations between ascorbate and ALS, and between albumin with PD." (PMID 37034095, 2023).